MIR411 (microRNA 411)
Synonyms: hsa-mir-411; MIRN411; mir-411
Gene: MicroRNA gene on chromosome 14 (101,023,325 to 101,023,420, forward strand). Ensembl gene ENSG00000199109.
Gene Ontology:
Biological process: miRNA-mediated post-transcriptional gene silencing
Cellular component: RISC complex
Homologues: Orthologues: chimpanzee ptr-mir-411 (100% identical), rat Mir411 (100% identical).